HSPB1 (heat shock protein family B (small) member 1)
Diseases named in the same sentence as HSPB1 in open-access papers (continued):
Sharing a sentence is not in itself a finding about the gene and the disease.
tumor (continued). "Notably, the absence of nuclear p-Hspb1 in differentiated DAergic neurons implies that its functions could be restricted to proliferative tumor cells rather than normal neurons." (PMID 39239519, 2024). "Therefore, to validate our hypothesis, a xenograft tumor model in M-NSG mice was further constructed by injecting SW620 stable cells transfected with HSPB1, and we observed that restoration of HSPB1 expression significantly promoted tumor growth in vivo, including tumor volume and weight." (PMID 38041016, 2023). "IGKC, SCGB1A1 HSPB1, and FCGR3A were found to be differentially expressed in normal tissue compared with tumor and metastasis." (PMID 37335089, 2023). "Incremented transcripts levels of HSPB1, HSPB9 and HSPB11 were observed in most BRCA subtypes, CRYAA was upregulated only in Basal subtype and ODF1 showed an increased expression in Luminal A tumours that was not significant by the Deseq2 method." (PMID 29954368, 2018).
neurodegenerative disease (17 papers, 2013 to 2026). A disorder of the central nervous system characterized by gradual and progressive loss of neural tissue and neurologic function. "Further investigation into the pathogenic mechanisms associated with HSPB1 is required to gain a more comprehensive understanding of the involvement of the BBB in neurodegenerative diseases." (PMID 37735671, 2023). "Pathogenic mutations of HSPB1 are associated with neurodegenerative diseases." (PMID 38664915, 2024). "In addition to a deficit in NF axonal transport, increased Cdk5 activation and hyperphosphorylation of NFs might as well directly affect axonal degeneration in HSPB1 mutants as both events have been associated with neurodegenerative diseases." (PMID 23728742, 2013). "HSPB1 as promising targets involved in the pathological mechanisms of neurodegenerative diseases, is upregulated in AD." (PMID 39872979, 2024). "Chaperones HSPB5 (also known as CRYAB) and HSPB1/HSP27 are overexpressed in neurodegenerative diseases and these heat shock proteins are conservative among different species." (PMID 34572572, 2021). "With regard to other neurodegenerative diseases, elevated serum levels of HspB1 have been reported during attacks in multiple sclerosis." (PMID 33192447, 2020). "Out of 10 mammalian sHSPs, four family members are expressed in neurons and play a role in neurodegenerative diseases: HSPB1, HSPB5, HSPB8 and to a lower extend, HSPB6." (PMID 33330614, 2020). "We therefore conclude that HSPB1 can mediate translational repression through interaction with an RNA binding protein further supporting its role in neurodegenerative disease." (PMID 28077174, 2017). "Hspb1 is upregulated in response to oxidative stress, brain injury, and neurodegenerative diseases." (PMID 38891920, 2024). "Mutations in BAG3, HSPB1, and CHIP have been linked to neurodegenerative diseases." (PMID 35164882, 2022). "By activating HSPB1 expression to reduce aggregation, ROS and cytotoxicity in ΔK280 TauRD‐DsRed‐expressing cells, LM‐031 could be a promising disease‐modifying compound for the treatment of AD and other oxidative stress‐related neurodegenerative diseases." (PMID 32496635, 2020). "HSPB1 and HSPA1A as promising targets involved in the pathological mechanisms of neurodegenerative diseases." (PMID 37735671, 2023). "Apart from this, insufficient axon transport is a common theme in many neurodegenerative diseases, and some researches have found that NEFL and HSPB1 (included in the GO term of axon transport) are closely related to axonal transport dysfunction of CMT." (PMID 33029488, 2020). "HSPB1 and HSPB5 are upregulated in neurodegenerative diseases, especially in reactive glial cells and HSPB8, together with BAG3, is upregulated in astrocytes." (PMID 33330614, 2020).
myopathies (13 papers, 2013 to 2025). "Small heat shock proteins, Hsp27 (Hspb1) and αB-crystallin increase titin-based passive tension and have been linked to various myopathies." (PMID 34745373, 2021). "We have taken advantage of this cell system to analyze the consequences of the expression of the myopathy- and cataract-causing R120G HspB5 mutant in cells that already express HspB1." (PMID 23950959, 2013). "Furthermore, depletion of Hspb1, another member of the sHSP family whose mutant form has also been associated with myopathy, leads to myofiber ultrastructural defects." (PMID 28780615, 2018). "Mutations in HSPB1, HSPB3, and HSPB8 cause motor neuropathies such as Charcot–Marie–Tooth disease and distal hereditary motor neuropathy, whereas mutations in HSPB5 are usually associated with myopathies." (PMID 37566026, 2023). "Skeletal muscle targeting by HSPB1 is not surprising since HSPB1 mutations (e.g., D129E and R140G) have been described in patients showing myopathy features." (PMID 35281256, 2022). "HSPB1 and HSPB7 have been shown to directly interact with FLNC to modulate its localization, unfolding, and aggregation, which are closely related to the occurrence and progression of myopathy." (PMID 37566026, 2023).
infection (12 papers, 2008 to 2025). The state of being infected such as from the introduction of a foreign agent such as serum, vaccine, antigenic substance or organism. "When analyzing the data from a proteomic study on SARS-CoV-2 infection we detected a peak of HSPB1 abundance at 6 h after infection, while in the data from a phospho-proteomic study we found a peak of the CK2 enzymatic activity at that same time point." (PMID 34930105, 2021). "Novel truncated proteoforms of MX1 were identified in infected cells and phosphorylation driven regulation of HSPB1 proteoforms was correlated with infection." (PMID 27451424, 2016). "The expression of HSPB1 was upregulated upon infection with the HuN4 strain and downregulated upon infection with the HuN4-F112 strain, and the differences between cells infected with HuN4 and HuN4-F112 strains were significant at 48 hpi (P<0.01)." (PMID 24465692, 2014). "Genes in group E were slightly up-regulated as early as 8 hpi during infection; some heat shock proteins, such as HSPB1, HSPA6, HSPA1B were found in this group." (PMID 18811943, 2008). "Similar to HSPB1, PSMA6 was also upregulated with HuN4 infection and downregulated when infected with HuN4-F112, and the difference at 48 hpi between them was significant (P<0.05), too." (PMID 24465692, 2014). "The validation of a number of differentially expressed proteins showed that the expression of PKM2, HSPB1, and PSMA6 was significantly different during the infection course between the virulent HuN4 strain and the attenuated HuN4-F112 strain." (PMID 24465692, 2014). "HSPB1 is also known as HSP27 and HSP28 and its levels are increased by mechanisms such as oxidative stress, heat shock exposure, infection, inflammation and ischemia." (PMID 23382852, 2013). "In the post-infection phase at three and ten months, there was persistent protein underexpression of pathways essential for cellular function, signaling, and homeostasis (AKT1, MAPK14, HSPB1)." (PMID 39324144, 2024). "However, we found no significant change in the expression of HSPB1 under a relatively low MOI infection of EV71." (PMID 35308396, 2022). "Validation of the gene expression levels obtained by RNA-seq specific to the HCV group (BIRC5 and SLC22A1), the HBV group (CLEC1B), and the group without infection (FGFR4, HSF1, RNF187, HSP90AB1, and HSPB1) was performed using the real-time PCR technique." (PMID 36557005, 2022).
peripheral neuropathy (10 papers, 2013 to 2022). A disorder affecting the peripheral nervous system. "HspB1 harbored by far most of the mutations as compared to HspB3 and HspB8: In a systematic study of a cohort of 510 unrelated index patients with peripheral neuropathies, 32 patients were found to have mutations in sHSPs (32/510; 6.3%)." (PMID 35678958, 2022). "So far, over 30 different mutations have been found in the HSPB1 gene leading to inherited peripheral neuropathies." (PMID 32323160, 2020). "In this study, we investigated the cellular pathomechanisms of peripheral neuropathy caused by missense mutations in the HSPB1 gene encoding for Hsp27." (PMID 28595321, 2017). "Here, we assessed the potential therapeutic effect of HDAC6 inhibitors on peripheral neuropathy with HSPB1 mutation using in vitro model of motor neurons derived from induced pluripotent stem cells (iPSCs) of CMT2F and dHMN2B patients." (PMID 28105056, 2016). "We previously showed that peripheral neuropathy causing HSPB1 mutants are hyperactive and bind more strongly to MTs causing their stabilization." (PMID 23826100, 2013). "HSPB mutations may have serious consequences, such as peripheral neuropathy caused by point mutations in HSPB1 and HSPB8." (PMID 36213445, 2022). "The autophagy deficits were also confirmed in motor neurons differentiated from patient-derived induced pluripotent stem cells (iPSCs), thereby indicating that the impairment of autophagy might be another pathomechanism by which mutations in HSPB1 cause a peripheral neuropathy." (PMID 32323160, 2020). "We hypothesize that mutant HSPB1 can mediate translational repression by forming an interaction with PCBP1 leading to an alteration in the expression levels of genes important to cause peripheral neuropathies." (PMID 28077174, 2017). "In this paper, we will first summarize how mutations in HSPB1, HSPB3, and HSPB8 cause hereditary peripheral neuropathies." (PMID 32323160, 2020). "Additionally, it is relevant that peripheral neuropathy can be caused by pathogenic variants in mitochondrial protein chaperones such as HSPB8 (HSP22), HSPB1(HSP27), and TID1, and that modulating chaperones can improve sensory fiber recovery in diabetic peripheral neuropathy." (PMID 33810506, 2021).
neurological diseases (7 papers, 2017 to 2024). "For example, PCBP1 has been reported to interact with HSPB1 mutants as well as other genes causing neurological disorders." (PMID 38376022, 2024). "Several previous studies have demonstrated that HSPB1 is upregulated upon neurological disorders; therefore, we used this transgenic strain to model the role of HSPB1 in neuroinflammation." (PMID 33423680, 2021). "By expanding our knowledge on HSPB1 function as an immunoregulatory factor, it could become a potential therapeutic target for fine-tuning neuroinflammation, which is a common pathological characteristic of most neurological disorders." (PMID 33423680, 2021). "We hypothesized that HSPB1 may be the core molecule of the shared pathological mechanism of the three diseases, which is the result of the induction by the blood–brain barrier (BBB) in response to cellular stress, providing insight into the nervous system diseases with unique pathogenic processes." (PMID 37735671, 2023). "This network shows a molecular link to HSPB1 to the crystallin chaperones, which are ZN2+ dependently activated and upregulated in neurological diseases." (PMID 35576218, 2022).
neuromuscular disease (3 papers, 2020 to 2022). "To date, mutations in the genes coding for HspB1, HspB3, HspB5, and HspB8 have been associated with neuromuscular diseases." (PMID 34487489, 2021). "Four of these sHSP genes carry known mutations which have been associated with neuromuscular disease phenotypes in humans: HspB1 (Hsp27, Hsp25), HspB3, HspB5 (αB-crystallin), and HspB8 (Hsp22), not counting polymorphisms or other sequence variants with unclear relation to disease." (PMID 35678958, 2022). "In this review, we cover mutations in DNAJB6, DNAJB2, αB-crystallin (CRYAB, HSPB5), HSPB1, HSPB3, HSPB8, and BAG3, and discuss the molecular mechanisms by which they cause neuromuscular disease." (PMID 32093037, 2020).
adenocarcinoma (1 paper, 2015). A common cancer characterized by the presence of malignant glandular cells. "Recently, the switch between apoptosis and survival, modulated by Akt stability, has been attributed to HSPB1/HSP27 in adenocarcinoma cells." (PMID 26108672, 2015).
brain disease (1 paper, 2024). "Astrocytic HSPB1 also increases when tau pathology in mice is restricted to neurons, suggesting that astrocytes respond with changes in HSPB1 across brain disease pathology and in response to a variety of stimuli." (PMID 38507480, 2024).
kidney diseases (1 paper, 2024). "Proteins linked to kidney diseases, including heat shock protein family B (small) member 1 (HSPB1), S100A6, transgelin (TAGLN), and TIMP metallopeptidase inhibitor 3 (TIMP3), were shown to be enriched in the proteome unique to AL." (PMID 38892061, 2024).
HSPB1 also shares sentences with these, for which no sentence is quoted: non-small cell lung carcinoma (4 papers); liver cancer (3); sarcoma (3); anemia (2); breast invasive carcinoma (2); cardiac hypertrophy (2); cholangiocarcinoma (2); Corticobasal Degeneration (2); gastric adenocarcinoma (2); lung squamous cell carcinoma (2); metabolic disorders (2); muscular atrophy (2); myofibrillar myopathy (2); Niemann-Pick disease type C (2); oligodendroglioma (2); paroxysmal AF (2); prostate adenocarcinoma (2); renal carcinoma (2); retinal degeneration (2); sarcopenia (2); Stroke (2); actinic keratosis (1); acute lymphoid leukemia (1); acute myeloid leukemia (1); acute pancreatitis (1); Alexander disease (1); anaplastic astrocytoma (1); Anxiety (1); aortic atherosclerosis (1); arthrogryposis (1).
A further 88 diseases each share a sentence with HSPB1 in 1 paper.